UCA1 (urothelial cancer associated 1)
Diseases named in the same sentence as UCA1 in open-access papers (continued):
Sharing a sentence is not in itself a finding about the gene and the disease.
breast cancer (continued). "The expression levels of long non-coding RNAs (lncRNAs) HOTAIR, MALAT1, and UCA1, as well as cancer stem cell-related genes FOX, SNAIL, and ZEB, were analyzed in metastatic breast cancer stem cells (MBCSCs) compared to a healthy control group." (PMID 40781106, 2025). "MALAT1, UCA1, CYTOR, HOTAIR, and GAS5 expressions were compared between breast cancer patients treated with tamoxifen alone (control) and those treated with tamoxifen plus NanoCurcumin (target group)." (PMID 41031251, 2025). "For instance, the functional ribonucleoprotein complex of UCA1 and PTBP1 promoted breast cancer growth by suppressing p27 mRNA level." (PMID 38273088, 2024). "In contrast, other circulating lncRNAs (H19, SPRY4‐IT1, XIST, UCA1, AC026904.1, CCAT1, CCAT2, ITGB2‐AS, and AK058003) were significantly up‐regulated in breast cancer patients compared to controls." (PMID 36274054, 2023). "In this study, we aimed to determine the expression of ANRIL, TUG1, UCA1, and HIT lncRNAs in breast cancer patients." (PMID 35132340, 2022). "Survival analysis of breast cancer patients were performed based on low (≤1 fold) or high (>1 fold) expression of lnc ANRIL, TUG1, UCA1, and HIT RNAs." (PMID 35132340, 2022). "An increase in the expression of serum lncRNAs ANRIL (p < 0.0001), UCA-1 (p = 0.004), and HIT (p < 0.0001) was observed in the distant organ metastatic breast cancer patients." (PMID 35132340, 2022). "It has been suggested that UCA1 confers endocrine-therapy resistance through EZH2/p21 axis and the PI3K/AKT signaling pathway in breast cancer." (PMID 35949302, 2022). "We found a significant increase in the expression of serum lncRNAs ANRIL (5.69 ± 2.78; p < 0.0001), UCA-1 (9.26 ± 4.58; p = 0.004), and HIT (7.37 ± 4.38; p < 0.0001) in the distant metastases positive breast cancer patients." (PMID 35132340, 2022). "Previous studies in the breast cancer cell line MDA-MB-231 also showed that lncRNA UCA1 promoted EMT through the Wnt/β-catenin signaling pathway, thereby promoting the invasion and metastasis of breast cancer cells." (PMID 36124026, 2022). "Increased ANRIL (3.83-fold), TUG1 (7.64-fold), UCA1 (7.82-fold), and HIT (3.31-fold) expressions were observed in breast cancer patients compared to healthy controls." (PMID 35132340, 2022). "Evidence from an in vitro study suggested that UCA1 silencing inactivates AKT and mTOR, augmenting tamoxifen-induced apoptosis in breast cancer cells." (PMID 34298879, 2021). "It has also been shown that the lncRNA AC026904 and UCA1 cooperatively increase Slug expression at both the transcriptional and post-transcriptional levels, thereby inducing EMT and metastasis in breast cancer." (PMID 34527584, 2021). "Based on what we observed in this study, we have proposed of putative model on how UCA1 up-regulates the expression of PTP1B and promotes breast cancer." (PMID 31695578, 2019). "This is the first time to establish a connection between UCA1 and PTP1B expression in breast cancer, and also to reveal the mechanism of PTP1B expression up-regulation by UCA1 through sequestering miR-206." (PMID 31695578, 2019). "Exosomes derived from tamoxifen-resistant breast cancer cells, LCC2, exhibited greater expression of UCA1 compared to sensitive cells (MCF7)." (PMID 31867576, 2019). "In breast cancer cells, IMP1 interacts with UCA1 via the “ACACCC” motifs within UCA1 and destabilizes UCA1 through the recruitment of CCR4-NOT1 deadenylase complex." (PMID 29669595, 2018). "Our data reveal that UCA1 upregulates the IGF-1R and PKM2 by competitively sponging miR-122-5p, and thus promotes the invasive potential of breast cancer cells." (PMID 29669595, 2018). "In line with previous studies on gastric and breast cancers, the Western blotting results demonstrated a reversed EMT markers after silencing of UCA1 in both CCLP1 and RBE cells." (PMID 29221199, 2017).
breast cancer (continued). "The results showed that lncRNAs AFAPA-AS1, aHIF, BDNF-AS, HYMAI, UCA1, kucg 1, MALAT1 were differentially expressed in breast cancer tissues (fold change > 2)." (PMID 28938549, 2017). "In the breast cancer cell line MDA-MB-231, lncRNA UCA1 contributes to the stimulation of EMT through Wnt/β-catenin signaling pathway, thus promoting the invasion and metastasis of breast cancer cells." (PMID 28738810, 2017). "When breast cancer cells are exposed to tamoxifen, the expression of HIF1-α increases, which stimulates over-expression of UCA1, and thereby enhances β-catenin translocation into the nucleus, promoting the extracellular redistribution of the ER." (PMID 29299178, 2017). "Flow cytometry analysis revealed that after the knockdown of lncRNA UCA1, the apoptotic of MCF-7-R and T47D-R cells was greatly enhanced upon tamoxifen treatment, which means lncRNA UCA1 would protect breast cancer cells from tamoxifen induced apoptosis." (PMID 27977766, 2016). "It should be also noted that our ERα-dependent lncRNA set does not contain most of the lncRNAs that were previously studied in breast cancer, such as HOTAIR, CCAT2, UCA1, MALAT1, BCAR4, EGOT, SPRY4-IT1 and others." (PMID 26621851, 2016). "Additionally, UCA1 regulates the EZH2/p21 axis and the PI3K/AKT signaling pathway, which are known to be pivotal in breast cancer progression and resistance to targeted therapies." (PMID 41031251, 2025). "This study aimed to explore the molecular pathways connecting the long non-coding RNAs (lncRNAs) HOTAIR, UCA1, and MALAT1 with breast cancer stem cell-related genes FOXC2, SNAIL, and ZEB, focusing on their involvement in transcriptional regulation, proliferation, and survival." (PMID 40781106, 2025). "LncRNA UCA1 was found to enhance the expression of ULBP2 and promote the detachment of soluble ULBP2 from the cell surface, making it resistant to NK cells-mediated killing in breast cancer." (PMID 38254782, 2024). "In the current study, we analyzed the expression profiles of TUG1, ANRIL, UCA1, and HIT lncRNAs in breast cancer patients and investigated the differential expression of four pairs of lncRNA to determine their oncogenic roles and associations with clinical and pathological features." (PMID 35132340, 2022). "The authors also found a negative correlation between UCA1 and p27Kip1 in breast cancer tissues by microarray analysis." (PMID 35456025, 2022). "Notably, the induced upregulation of UCA1 in T47D and MCF7 breast cancer cells decreases the tamoxifen drug sensitivity." (PMID 35178359, 2021). "For instance, trastuzumab resistance has been reported in breast cancer by AGAP2-AS1 and SNHG14, whereas UCA1 was responsible for tamoxifen resistance in breast cancer, cisplatin resistance in ovarian cancer, and cetuximab resistance in metastatic colorectal cancer." (PMID 34067896, 2021). "In addition, from a previous study using breast cancer cell lines, such as MCF7 and BT474, it is shown that UCA1 acts as a ceRNA by sponging miR-18a to upregulate a target of miR-18a, the hypoxia-inducible factor 1α (HIF1α)." (PMID 32486413, 2020). "When UCA1 is present in the cells, UCA1 can bind miR-206 at a more favorable affinity than PTP1B, and this will protect mRNA of PTP1B from miR-206, so PTP1B can be over expressed which will then promote the growth of breast cancer tumor cells." (PMID 31695578, 2019). "Similarly, the regulation of UCA1 in As‐induced decreased expression of EZH2 was testified in multiple cell lines, including human prostate cancer cell line PC3, human breast cancer cell line 231, human lung adenocarcinoma cell line A549, and normal human kidney cell line HK2." (PMID 32537408, 2020). "Interestingly, we found that UCA1 could up-regulate PTP1B expression via sequestering miR-206 at post-transcription level, which led to the promotion of breast cancer." (PMID 31695578, 2019).
breast cancer (continued). "The expression of lncRNA UCA1 was dramatically increased in the tamoxifen-resistant MCF-7 and T47D cells compared with their parental cells, suggesting that lncRNA UCA1 may play important roles in the tamoxifen resistance of breast cancer." (PMID 27977766, 2016). "According to pathological grading, all 54 cases of breast cancer were classified as grade I, II, III and IV, then were divided into two stage I+II group and stage III+IV group, and the expression level of lncRNA UCA1 was determined using quantitative RT-PCR (qRT-PCR)." (PMID 27977766, 2016). "However, whether UCA1 plays any roles in the acquired tamoxifen resistance in breast cancer is not reported so far." (PMID 27977766, 2016). "In this sense, from the generated data, we evidence here two lncRNAs, UCA1 and HCP5, which have not yet been identified in the context of the tumoral immune response in breast cancer." (PMID 37835376, 2023). "We observed that the breast cancer patients have low and high expression in ANRIL, TUG1, and HIT lncRNAs and none patients who had low expression in UCA1." (PMID 35132340, 2022). "Similar to these observations, our study shows that knockdown of HIF-1α, but not HIF-2α, in breast cancer cells induced a significant decrease in UCA1 expression, suggesting that HIF-1α is a direct regulator of UCA1 in MCF-7 under hypoxic conditions." (PMID 34054950, 2021). "However, the connection between UCA1 and PTP1B in breast cancer is not well studied." (PMID 31695578, 2019).
colorectal cancer (72 papers, 2015 to 2025). A primary or metastatic malignant neoplasm that affects the colon or rectum. "Expression levels of the blood plasma/serum BLACAT1, CCAT1, CRNDE, CCAT2, NEAT1, and UCA1 were found to have diagnostic potential in colorectal cancer." (PMID 37569782, 2023). "Circulatory biomarker: Diagnostic values of circulatory UCA1 has been reported in other cancers, such as bladder, gastric cancer, and colorectal cancer." (PMID 34322395, 2021). "Urothelial carcinoma associated 1 (UCA1), located on chromosome 19p13.12, is an intergenic lncRNA involved in several cancers, such as lung, breast, gastric, and colorectal cancers, as well as glioma." (PMID 34322395, 2021). "LncRNA urothelial cancer associated 1 (UCA1) is abnormally expressed in esophageal squamous cell carcinoma, colorectal cancer, gastric cancer melanoma cells, pancreatic cancer, thyroid cancer, lung cancer and so on." (PMID 31996265, 2020). "In the second part of this review, we focus on the role of lncRNA Urothelial Cancer Associated 1 (UCA1) to integrate research in different types of cancer in order to decipher its putative function and mechanism of regulation in colorectal cancer cells." (PMID 30441811, 2018). "We studied the association between UCA1 expression and clinicopathological characteristics in esophageal cancer, colorectal cancer and pancreatic cancer." (PMID 28380443, 2017). "Upregulated UCA1 is associated with tumor progression through targeting miR-193a-3p, miR-204-5p in non-small cell lung cancer and colorectal cancer individually." (PMID 27713161, 2017). "Recent preliminary studies reported the in vitro tumor-promoting effects of long non-coding RNA urothelial carcinoma associated 1 (UCA1) in colorectal cancer (CRC)." (PMID 27046651, 2016). "This investigation was arranged to elucidate whether single nucleotide polymorphisms (SNPs) of lncRNA UCA1 was implicated in elevating colorectal cancer (CRC) risk by interacting with environmental exposures." (PMID 32143722, 2020). "Further, our analysis revealed that a high UCA1 expression level is significantly associated with advanced T category, late clinical stage, and worse prognosis, and these findings are consistent with those in other cancers, such as colorectal cancer and ovarian cancer." (PMID 28327194, 2017). "UCA1 expression causes cisplatin resistance of OSCC cells and radioresistance in prostate and colorectal cancers." (PMID 40568293, 2025). "Another study showed that UCA1 facilitates 5-FU resistance by colorectal cancer cells by increasing autophagy and preventing apoptosis through sponging miR-23b-3p." (PMID 36499136, 2022). "On the contrary, the knockdown of lncRNA UCA1 is responsible for the radiosensitization of colorectal cancer cells through the induction of radiation-induced cell cycle arrest and apoptosis." (PMID 36499136, 2022). "The overexpression of lncRNA UCA1 promotes the proliferation of colorectal cancer cells and contributes to 5-FU resistance by inhibiting 5-FU-induced apoptosis." (PMID 36499136, 2022). "On the other hand, the downregulation of UCA1 increases the sensitivity of colorectal cancer cells to 5-FU by increasing apoptosis." (PMID 36499136, 2022). "In colorectal cancer, UCA1 was upregulated in the patients’ serum exosomes and increased the ability of proliferation and migration in cancer cells." (PMID 33743811, 2021). "Highly expressed lncRNA UCA1 is also reported in colorectal cancer (CRC) cells and contributed to tumorigenic activity." (PMID 33936199, 2021). "Interaction between UCA1 and miR-204-5p enhances cell growth and 5-fluorouracil resistance in colorectal cancer." (PMID 33204264, 2020). "UCA1 is highly expressed in breast, gastric and colorectal cancers, indicating a common important role in human cancers." (PMID 29669595, 2018). "UCA1 enhances cell proliferation and 5‐fluorouracil resistance by inhibiting miR‐204‐5p in colorectal cancer." (PMID 29516678, 2018).
colorectal cancer (continued). "Another lncRNA, UCA1, enhances 5-fluorouracil resistance of colorectal cancer by inhibiting miR-204-5p." (PMID 28831025, 2017). "Another lncRNA, UCA1, enhances 5-fluorouracil resistance in colorectal cancer by inhibiting miR-204-5p." (PMID 29212230, 2017). "For instance, UCA1 promoted cell proliferation and conferred 5‐fluorouracil resistance in colorectal cancer." (PMID 29125238, 2017). "The clinicopathological value of UCA1 was further analyzed in esophageal carcinoma, colorectal carcinoma and pancreatic carcinoma." (PMID 28380443, 2017). "UCA1 has been found significantly up-regulated in most tumors and cancer cells, including colorectal cancer." (PMID 27148353, 2016). "UCA1 putatively influences the proliferation, apoptosis, and cell cycle progression of colorectal cancer cells." (PMID 27329842, 2016). "Han and collaborators found that UCA1 levels were markedly increased in colorectal cancer tissues and cells, and that they influenced proliferation, apoptosis and cell cycle progression of colorectal cancer cells." (PMID 27148353, 2016). "In colorectal cancer, UCA1 was found to function as an endogenous sponge by directly binding to miR-204-5p and promote the expression of a new target of miR-204-5p, CREB1." (PMID 28074092, 2016). "Exosomal MALAT1 and UCA1 serve as pro-metastatic factors in colorectal cancer." (PMID 35055115, 2022). "UCA1 is highly expressed in colorectal cancer tissues, cell lines, and patients’ serum exosomes." (PMID 35055115, 2022). "Colorectal cancer patients with a higher UCA1 expression had a poorer prognosis." (PMID 33743811, 2021). "Here, UCA1 was confirmed to be highly expressed in colorectal cancer." (PMID 34733326, 2021). "In this study, we aimed to determine whether RNA methylation at N6-methyladenosine (m6A) can impact UCA1 expression in colorectal cancer (CRC)." (PMID 34809621, 2021). "UCA1 was confirmed to be highly expressed in colorectal cancer." (PMID 34733326, 2021). "In colorectal cancer cells, UCA1 expression is induced by conditioned medium from CAFs." (PMID 33050576, 2020). "Besides, UCA1 worked as an oncogene in other cancers, including colorectal cancer, ovarian cancer, and GC." (PMID 33204264, 2020). "These include but are not restricted to lncRNAs like HOTAIR, Pvt1, RoR, prostate cancer–associated transcript 1 (PCAT1), ANRIL, H19, nuclear enriched abundant transcript 1 (NEAT1), UCA1, lung adenocarcinoma transcript 1 (LUADT1), colorectal cancer–associated lncRNA (CCAL), and many more." (PMID 30296263, 2018). "Furthermore, we discuss the role of UCA1 in the regulation of cell cycle progression and its relation to chemoresistance in colorectal cancer cells." (PMID 30441811, 2018). "Furthermore, it was shown that lncRNA UCA1 sequesters miR-204-5p in colorectal cancer and reduces the level of this microRNA in cancer cells." (PMID 29967761, 2018). "UCA1 has been studied in a wide range of cancer cells, including colorectal cancer." (PMID 30441811, 2018). "Furthermore, the clinicopathological values of UCA1 were discussed in esophageal cancer, colorectal cancer and pancreatic cancer." (PMID 28380443, 2017). "So far, the overexpression of UCA1 has been reported in other cancers, especially in digestive system malignancies, including hepatocellular carcinoma, gastric cancer, colorectal cancer, pancreatic cancer, and esophageal squamous cell carcinoma." (PMID 28074092, 2016). "In colorectal carcinoma, for example, overexpression of UCA1 was illustrated to promote proliferation and cell cycle progression and inhibit apoptosis, whereas suppression of UCA1 inhibited cell proliferation and cell cycle progression and facilitated apoptosis." (PMID 28074092, 2016). "Down-regulation of UCA1 has been shown to enhance radiosensitivity and inhibit cell migration by suppressing EMT in colorectal cancer cells." (PMID 35949302, 2022).
colorectal cancer (continued). "For instance, UCA1 deletion suppressed cell invasion and colony survival fraction, and induced cell cycle arrest by inhibiting EMT progression in colorectal cancer." (PMID 32943997, 2020). "It was previously shown that WNT6 expression is positively regulated by CAV1 (a scaffolding protein), UCA1 (a long noncoding RNA), and PLAGL2 (a zinc finger protein) in gastric, bladder, and colorectal cancer, respectively." (PMID 31923345, 2020). "UCA1 is involved in the promotion of the proliferation, migration, invasion, and EMT of colorectal cancer cells, which is mediated by blocking miR-143 and relieving KRAS inhibition." (PMID 33050576, 2020). "By analyzing the expression of 17 lncRNAs and 31 circRNAs in biopsies and serum exosomes from colorectal cancer (CRC) patients through qRT-PCR, we detected CCAT1, CCAT2, HOTAIR, and UCA1 upregulation and CDR1AS, MALAT1, and TUG1 downregulation in biopsies." (PMID 30195762, 2018). "UCA1, which was upregulated in 10 EOC studies, also showed increased levels in serum-derived exosomes from cisplatin-resistant OC patients and plasma from colorectal cancer patients." (PMID 37445988, 2023). "Several studies have suggested that exosomal forms of lncRNAs (91H, CRNDE-h, UCA1, TUG1, LNCV6_116109, LNCV6_98390, LNCV6_38772, LNCV6_108226, LNCV6_84003, LNCV6_98602) have potential as additional markers for diagnosis, prognosis, and response to therapy of patients with colorectal cancer." (PMID 37569782, 2023). "In normal colonic FFPE tissue samples, no UCA1 ISH signal was detected, whereas UCA1 ISH signal was observed in adenoma tissue and an even stronger signal was detected in colorectal carcinoma samples, in accordance with our qRT-PCR results." (PMID 31694571, 2019).